SSTR2 (somatostatin receptor 2)
Diseases named in the same sentence as SSTR2 in open-access papers (continued):
Sharing a sentence is not in itself a finding about the gene and the disease.
tumor (continued). "Well-differentiated SI and pancreatic NENs generally express high levels of SSTR2, especially in tumours with a low Ki-67 index (≤2%)." (PMID 36980746, 2023). "Given her primary tumour's somatostatin receptor type 2 (SSTR2) positivity, gallium-68 DOTA-[Tyr3] octreotate PET CT (68Ga-DOTATATE PET CT) was performed, revealing multiple distant metastases with DOTATATE avidity." (PMID 38352266, 2023). "Activation of SSTR2 inhibits the migration and proliferation of these cells, which reduces the formation of new vessels and reduces tumor growth." (PMID 38201544, 2023). "Tumor heterogeneity of SSTR2 expression can be observed within a lesion or among different lesions in the same patients." (PMID 37444593, 2023). "Efficient blockage of the tumor uptake with co-injection of an excess of unlabeled ligand was observed at 24 h p.i. for all three radioligands, demonstrating specificity towards SSTR2." (PMID 37513897, 2023). "We also observed a strong correlation between SSTR2 and CD8+ T cells, B cells, T cells, tumor-associated macrophages (TAMs), M2 macrophages, neutrophils, DCs, T helper type 1 (Th1) cells, Tfh cells, regulatory T cells (Tregs), exhausted T cells, and monocytes." (PMID 37900156, 2023). "This indicates the potential to persistently upregulate SSTR2 expression, even after removal of the drug, facilitating tumor uptake of 177Lu-DOTATATE." (PMID 37487000, 2023). "Decreased tumour growth was also reported in animal models where the SSTR2 gene was introduced artificially." (PMID 38203605, 2023). "The relative expression of SSTR2 is also variable in different control and tumor tissues but observed frequently." (PMID 38203605, 2023). "The sAOT is a good predictor tool for assessing response to SRLs and correlates with tumor E-cadherin and SSTR2 expression." (PMID 38027102, 2023). "While SSTR2 expression is used to predict response to SSAs, the correlation between the pattern of expression of SSTR2 on tumour cells and the therapeutic response to SSAs is unclear as the available evidence is limited to only a few selected cases." (PMID 36980746, 2023). "Eight independent G1, G2 (n.5) and G3 (n.3) PanNET FFPE tumor tissue specimens were first reviewed by an expert pathologist for SSTR2 expression level." (PMID 37287922, 2023). "SST and its analogs have been shown to inhibit tumour growth in colorectal cancer cell lines and models positive to SSTR2 both in vivo and in vitro." (PMID 38203605, 2023). "The only other tumor with a comparably high cell expression of SSTR2 and high intensity grading was a NEC." (PMID 37568733, 2023). "Beyond symptomatic management, recent research demonstrates that SSAs exert antiproliferative effects and inhibit tumour growth via the somatostatin receptor 2 (SSTR2)." (PMID 37434648, 2023). "The researchers found that the combination of SST and SSTR2 inhibits cytokine release from immune cells and impacts the tumor microenvironment (TME)." (PMID 37900156, 2023). "Variability in tumor blood flow and tumor blood volume appeared most important to predict tumor uptake population ranges, while SSTR2 expression differences seemed less relevant." (PMID 36735114, 2023). "Somatostatin receptors specifically somatostatin receptor subtype 2 (SSTR2) is overexpressed in paediatric tumours, including medulloblastoma and primitive neuroectodermal tumours (PNET)." (PMID 36673002, 2023). "Intra-tumour and inter-tumour (between primary and metastatic disease) heterogeneity in the expression of SSTR2 in NENs has also been demonstrated." (PMID 36980746, 2023). "SSTR2 is expressed in many NENs, and immunostaining for SSTR2 is useful in assessing tumor differentiation and estimating the effects of somatostatin analog therapy." (PMID 35267427, 2022). "The control cells formed rapidly growing tumors, whereas SSTR2-OVER cells formed tumors that were much smaller, suggesting that SSTR2 has tumor suppressor activity and is a negative regulator of tumor growth both in vitro and in vivo." (PMID 36551669, 2022).
tumor (continued). "[90Y]Y-EB-TATE showed higher tumor uptake and improved tumor response in mice bearing SSTR2-positive tumors compared to [177Lu]Lu-DOTA-TATE." (PMID 36145375, 2022). "In this study, we developed a methodology to understand and further improve the absorbed dose characterization of peptide receptor radionuclide therapy during in vivo experiments using the SSTR2 expression of tumor xenografts." (PMID 33837068, 2022). "Analysis of tumor regions revealed 2-foldhigher signal in SSTR2+ tumors for mice receiving MMC(FNIR-Tag)-TOC,whereas the cohort injected with the IR800 conjugate had identicalfluorescence intensities in both tumors." (PMID 36174110, 2022). "In our study, age was associated with SSTR2 expression in that patients with TET that expressed SSTR2 in at least 50% of the tumor cells were significantly younger than patients with TET that expressed SSTR2 in 1-49% of tumor cells." (PMID 35198446, 2022). "Tissue sections were stained with an anti-SSTR2 antibody and a high and homogeneous expression of the receptor was observed throughout the entire tumor tissue." (PMID 35745856, 2022). "To assess the molecular mechanism of how SSTR2 contributes as tumor suppressor in vitro, we performed RNA-seq analysis for SSTR2-KO or SSTR2-OVER cells, followed by a pathway enrichment analysis based on the detected DEGs." (PMID 36551669, 2022). "By using ssGSEA analysis, we found that T cell signature tends to enrich the tumor microenvironment in SSTR2-high groups in most cancers (96.15%)." (PMID 35264912, 2022). "[68Ga]Ga-DOTA-TATE PET scans are a suitable method for monitoring tumor size in SSTR2-positive AR42J tumors in mice." (PMID 36551858, 2022). "Single-cell multiplex imaging of immunosuppressive immune cells neighboring SSTR2+ tumor cells will facilitate advances in understanding the complex radioligand–tumor cell interactions within the tumor microenvironment." (PMID 35890361, 2022). "The biodistribution of [68Ga][Ga(THP-TATE)] in Balb/c nu/nu mice bearing SSTR2-positive AR42J tumours showed a clear delineation of the tumour as well as radiation uptake in the kidneys." (PMID 36615397, 2022). "Image analysis revealed that the NIR-fluorescence signal was localized only in the NEC913(SSTR2+) tumor." (PMID 35454817, 2022). "The reason for this is most likely related to the fact that [177Lu]Lu-DOTA-TATE reaches the tumor by active targeting, i.e., by binding to SSTR2." (PMID 35745856, 2022). "Both compounds were labeled with lutetium-177, and their in vivo distribution in tumor xenografts, overexpressing SSTR2 were investigated by SPECT/CT imaging and ex vivo biodistribution." (PMID 36145375, 2022). "In the earlier time points, pronounced uptake in pancreas was observed in both healthy and tumor-bearing animals, in line with endogenous expression of the SSTR2 in this organ." (PMID 36559060, 2022). "To validate the dual function of SSTR2 as an imaging reporter and a suicide switch, we have used subcutaneous tumors to clearly delineate tumor-infiltrating CAR T cells by PET/CT from those expanding outside of tumor." (PMID 36463361, 2022). "PRRT relies on α- and β- emitting radionuclides bound to a peptide targeting SSTR2 that are administered intravenously to the patient and travel towards the tumor." (PMID 35745856, 2022). "In vitro uptake of these compounds in cells and tumor sections expressing SSTR2 was lower than the uptake of JR11." (PMID 36145375, 2022). "Results on prior imaging assessment of somatostatin receptor subtype 2 (SSTR2) were available in six patients, all of which demonstrate tumour uptake of tracer." (PMID 36018781, 2022). "Nonetheless, the observed increase in [177Lu]Lu-DOTATATE circulation time can lead to an increased radiotracer uptake in both high (e.g., tumor, pancreas and stomach) and low (e.g., liver, spleen and lung) SSTR2-expressing organs." (PMID 35057069, 2022).
tumor (continued). "Tumor-to-kidney ratios were compared in a AR42J (endogenous expression of SSTR2) xenografted mouse model injected with 55Co, 64Cu and 68Ga-labeled DOTA-TATE." (PMID 36559060, 2022). "SSTR2 are not only expressed by neuroendocrine neoplastic cells, but also by some tumor-infiltrating B-cells." (PMID 35890361, 2022). "Diagnostic imaging with SRS and 68 Ga-DOTATOC PET-CT and immunostaining with SSTR2 provide information on SSTR expression status in the tumor, which combined with an octreotide loading test helps to predict the response to SSA treatment." (PMID 35265125, 2022). "The radiation-induced toxicity can be a result of blocking the SSTR2 in the tumor and other physiological organs, leads to higher [177Lu]Lu-DOTATATE renal exposure." (PMID 35057069, 2022). "Here, we used SSTR2 levels as inputs to model tumor (cancer/healthy cells) and activity heterogeneity on a cellular scale." (PMID 33837068, 2022). "The signal from [64Cu]Cu-DOTA-TATE was homogeneous throughout the tumors, and thereby also in accordance with the uniform SSTR2 tumor expression observed through immunohistochemistry." (PMID 35745856, 2022). "Recently, the antitumor effects of 177Lu-DOTA-TATE were enhanced by PARP inhibitors (talazoparib) in somatostatin receptor 2-expressing tumor models." (PMID 36005176, 2022). "As compared to those with lower SSTR2 expression (1-49% of tumor cells), those with ≥ 50% tumor cells expression were younger in age (p=0.023)." (PMID 35198446, 2022). "To further evaluate SSTR2-specific cytotoxicity of PEN-221 in vivo, we used a bilateral tumor model by subcutaneously implanting Jurkat-SSTR2 and Jurkat-NT cells into the opposite flanks of the same NSG-MHC-KO mice." (PMID 36463361, 2022). "PRRT remains a newly introduced therapeutic option for NEN patients that targets somatostatin receptor 2 and 5 on the surface of the tumour cells." (PMID 35931878, 2022). "After confirming the expression of SSTR2 and the tumor uptake of DOTA-TATE in our setup, we moved on to evaluating a combination therapy consisting of [177Lu]Lu-DOTA-TATE-assisted PRRT and NS-based PTT." (PMID 35745856, 2022). "As anticipated, mice treated with PEN-221 after three doses exhibited nearly complete regression of the Jurkat-SSTR2 tumor." (PMID 36463361, 2022). "SSTR2 immunohistochemistry was performed on tumour samples from eight of the patients who underwent [68 Ga]Ga-DOTATATE PET/CT (patient 002, 003, 004, 005, 006, 007, 009 and 010)." (PMID 33443647, 2021). "SST analogues (Octreotide, Lanreotide, and Pasireotide (for SSTR2,5)) are widely used as first-line treatment for perioperative period, metabolic diseases, and tumor control." (PMID 33796080, 2021). "The resulting Ga‐DOTA‐ICC‐TATE probe was examined in cell experiments and in an SSTR2‐overexpressing tumor mouse model to evaluate its targeting and imaging properties on the in vitro, in vivo and ex vivo level." (PMID 33238069, 2021). "SSTR2 selective tumor uptake was confirmed by saturating (blocking) SSTR2 using DOTA-TATE, followed by 800CW-TATE administration." (PMID 33768405, 2021). "SSTR2-specific binding was measured by comparing tumor uptake in NCI-H69 and CH-157MN xenografts, blocking experiments and non-targeted IRDye800CW-carboxylate binding." (PMID 33768405, 2021). "The first step would be to evaluate the tumor specimen from the nasopharynx or other regional/distant sites for the expression of SSTR2 on immunohistochemistry." (PMID 34638429, 2021). "In this report, we show that AE enters tumor cells via two of the five somatostatin receptors: SSTR2 and SSTR5." (PMID 33990938, 2021). "The uptake of [68Ga]Ga-DOTATOC was shown to correlate with the tumour size and percentage of SSTR2-expressing T-cells." (PMID 34439195, 2021). "[64Cu]Cu-SARTATE uptake was highest in the viable, SSTR2-positive regions of NB tumors, and cleared rapidly from non-tumor tissue." (PMID 33630166, 2021).
tumor (continued). "SSTR2 also induces tumor cell apoptosis by several mechanisms including upregulation of death receptor 4 and tumor necrosis receptor 1, and downregulation of the anti-apoptotic protein, Bcl-2." (PMID 34680266, 2021). "SSTR2s are expressed in a variety of tumor types, which has led to the use of SSTR2-targeting analogs for diagnosis and treatment." (PMID 35058882, 2021). "While most normal cell types express somatostatin receptors, several tumor types overexpress the somatostatin receptor type 2 (SSTR2)." (PMID 34359318, 2021). "Recent research has demonstrated that SSAs exert antiproliferative effects and inhibit tumor growth by binding the SSTR2." (PMID 33466160, 2021). "Due to the high linear energy transfer (80–100 keV/μm), alpha particles have the potential to eradicate somatostatin receptor subtype 2 (SSTR2) expressing tumor cells by producing irreparable DNA double-strand breaks while sparing normal tissue." (PMID 34959413, 2021). "The neuroendocrine origin of the tumor spheroids was confirmed by immunoblotting analysis of neuroendocrine biomarkers: chromogranin A (CgA), somatostatin receptor 2 (SSTR2), and synaptophysin (SYP)." (PMID 34065268, 2021). "[68Ga]Ga-DOTATOC has been used to visualise the biodistribution and tumour infiltration of SSTR2-expressing human T-cells in a Jurkat cell murine tumour model." (PMID 34439195, 2021). "The majority (74%) of patients had grade 1 or 2 tumours and 33% of patients had evidence of expression of either SSTR2 or SSTR5 in CTCs." (PMID 33494364, 2021). "In the present case, both the primary tumor and liver metastasis showed well-differentiated morphology and expressed typical neuroendocrine markers (chromogranin A and SSTR2), which indicated the liver metastasis to be well-differentiated NET-G3." (PMID 33742297, 2021). "800CW-TATE demonstrated sufficient binding affinity, specific SSTR2-mediated tumor uptake, a favorable biodistribution, and high TBR." (PMID 33768405, 2021). "SSTR2 staining in the tumor is evident in the section below and corresponds with high uptake in the autoradiogram of the same tissue sample." (PMID 33630166, 2021). "Radiolabeled somatostatin analogues (SSAs) were initially developed for the purpose of imaging SSTR type 2 (SSTR-2) expressions in gastroenteropancreatic (GEP)-NETs as these generally express SSTR-2 correlated to tumor grade." (PMID 34439519, 2021). "Tumor uptake was determined by injecting 800CW-TATE in (SSTR2-positive) NCI-H69 or (SSTR2-negative) CH-157MN xenograft bearing mice and FMT2500 imaging." (PMID 33768405, 2021). "SSTRs, especially SSTR subtype 2 (SSTR2) are found expressed at relatively higher levels in many tumor cells and in tumor blood vessels relative to normal tissues." (PMID 34203805, 2021). "Histological ex vivo examination using fluorescence microscopy showed high specificity of the hybrid probe for the SSTR2‐overexpressing tumor in comparison to the wild‐type tumor." (PMID 33238069, 2021). "In the present study, we found varying SSTR2 expression in tumor lesions from SI-NET patients, which is concordant with other studies." (PMID 33922482, 2021). "When 800CW-TATE is injected systemically in SSTR2-expressing tumor-bearing mice, it will bind to SSTR2 via the targeting octreotate peptide, but also to necrotic tissue via IRDye800CW." (PMID 33970376, 2021). "Autoradiography and histological analysis confirmed [64Cu]Cu-SARTATE uptake in viable, SSTR2-positive tumor regions with mean tumor uptakes of 14.1–25.0% IA/g at 24 h." (PMID 33630166, 2021). "The SSTR2 score correlated in all tumor samples within a patient, when sorted according to SSTR2 score in the primary tumor." (PMID 33922482, 2021). "[68Ga]Ga-DOTATATE uptake and immunohistological SSTR2 staining were positive in all patients and tumor samples, respectively." (PMID 33916640, 2021).
tumor (continued). "Using radionuclide and fluorescence imaging modalities, we performed SSTR2‐imaging in vitro, in vivo and ex vivo in SSTR2‐expressing cell and tumor mouse models." (PMID 33238069, 2021). "In vitro studies have shown that dexamethasone treatment of At-T20 corticotroph tumor cells induced significant suppression of SSTR2 messenger ribonucleic acid (mRNA) expression." (PMID 35058882, 2021). "There are several possible mechanisms of opioids to inhibit the biological behavior of tumor cells, including direct action on receptor or somatostatin receptor SSTR2." (PMID 34912457, 2021). "A higher magnification image of this deposit and (far right) a high magnification image of the IHC primary omission control on a contiguous section clearly shows these are tumor cells expressing SSTR2." (PMID 33630166, 2021). "On the basis of its robust tumour growth properties, in vivo SSTR2 expression and response to LuTate PRRT, the AR42J line was then used to explore the ability of a PARP inhibitor to potentiate the effects of LuTate treatment in vitro and in vivo." (PMID 32576907, 2020). "The heterogeneity of tumor characteristics (such as tumor subtype, growth rate, SSTR-2 expression, functional state, and imaging characteristics) causes difficulty when performing comparative research on NETs." (PMID 32024533, 2020). "PRRT holds great promise for the treatment of NET and our studies using a well characterised SSTR2-expressing preclinical tumour model demonstrate that the anti-tumour activity of LuTate PRRT can be enhanced by the PARPi, talazoparib." (PMID 32576907, 2020). "The [18F]FET-TOCA library was evaluated in vitro and in vivo to select an optimal radioconjugate for PET imaging of SSTR2 positive tumours." (PMID 32252406, 2020). "The uptake of the [18F]FET-TOCA library into key tissues was evaluated in mice bearing high SSTR2-expressing AR42J and low SSTR2-expressing HCT116 tumour xenografts." (PMID 32252406, 2020). "Biodistribution studies in SSTR2 positive tumor mice showed high specific uptake of [18F]AlF-NOTA-octreotide in the tumor and in SSTR2-expressing tissues with little or no in vivo defluorination." (PMID 31997090, 2020). "Biodistribution studies in SSTR2 positive tumor mice showed high specific uptake of [18F]AlF-NOTA-octreotide in the tumor and in SSTR2-expressing tissues, such as the pancreas, adrenal glands and the stomach with little or no in vivo defluorination in mice." (PMID 31997090, 2020). "The PET images showed very high tracer binding in the SSTR2 transfected H1299-7 model with a tumour to background binding ratio (TBR) of 159 ± 14 as determined by semiquantitative analysis." (PMID 32576907, 2020). "In PRRT, different radionuclides bind to cancerous cells expressing somatostatin receptors (SSTR), mainly SSTR2, allowing the internalization of the radionuclide that delivers radiation directly inside the tumor cell." (PMID 32668761, 2020). "The tumour models were evaluated for SSTR2 expression in vivo by 68Ga-DOTA-octreotate (GaTate) PET imaging." (PMID 32576907, 2020). "Further research showed that miR-185 targeted SSTR2 mRNA to downregulate SSTR2 protein expression, promote proliferation, and inhibit apoptosis of tumor cells, which would be classified as an oncogene in GH-secreting PA cells." (PMID 33023145, 2020). "[18F]AlF-NOTA-octreotide is a promising tracer that combines a straightforward Al18F-based production procedure with excellent in vivo pharmacokinetics and specific tumor uptake, demonstrated in SSTR2 positive tumor mice." (PMID 31997090, 2020). "Using a robust tumour model endogenously expressing high levels of SSTR2, we demonstrated for the first time the in vivo efficacy of LuTate PRRT in combination with a PARP inhibitor." (PMID 32576907, 2020). "In contrast, when the cells were grown as tumour xenografts in vivo, SSTR2 expression was primarily localised to the cell membrane (lower)." (PMID 32576907, 2020).